NTRK3 (neurotrophic receptor tyrosine kinase 3)
Diseases named in the same sentence as NTRK3 in open-access papers (continued):
Sharing a sentence is not in itself a finding about the gene and the disease.
tumor (continued). "Fusions of neurotrophic tropomyosin receptor kinase genes NTRK1, NTRK2 and NTRK3 with various partner genes have been detected in a variety of both common and rare tumour entities." (PMID 34372873, 2021). "Mechanistically, miR-128-3p and NTRK3 have been identified as a tumor suppressor and an oncogene, respectively." (PMID 33575204, 2020). "Combining our findings obtained with miR-128-3p and NTRK3, it appears that miR-128-3p exerts its tumor suppression by inhibiting the carcinogenesis of the oncogene, NTRK3." (PMID 33575204, 2020). "Further, probable tumor suppressors also include TrKC and the Nt-3 receptor (NtRK3), with genetic and epigenetic changes causing their activation in CRC." (PMID 32429087, 2020). "Taken together, the data provide robust evidence indicating that miR-128-3p can function as a tumor suppressor by inhibiting carcinogenesis of the oncogenic NTRK3." (PMID 33575204, 2020). "It has been reported that pan-Trk IHC is highly sensitive and specific for NTRK3 fusion-positive tumor detection." (PMID 33127954, 2020). "More importantly, animal experiments showed that tumor formed by A554 cells increase tumor size and weight, and accompanied by decreased expression of NTRK3 and increased expression of Ki-67." (PMID 27351280, 2016). "For example, we found six cancer types with a single fusion in a gene of the NTRK family, but altogether, we detected a total of 23 NTRK1, NTRK2 and NTRK3 fusions across nine tumour types." (PMID 25204415, 2014). "Previous studies have demonstrated that the activation of the MAPK and PI3K pathways by NTRK3 promotes cell differentiation, which in turn affects tumor progression." (PMID 23874207, 2013). "In the present study, we have provided evidence that NTRK3 can have conditional tumor suppressor activities in CRC." (PMID 23874207, 2013). "NTRK3 reconstitution significantly suppressed tumor growth compared to xenografts containing a control vector." (PMID 23874207, 2013). "We also performed studies on anchorage independent growth and tumor xenograft formation in established CRC cell lines to assess the putative tumor suppressor role of NTRK3 in CRC." (PMID 23874207, 2013). "In summary, we have identified NTRK3 as a novel conditional tumor suppressor gene in the colon that is inactivated by epigenetic and genetic mechanisms." (PMID 23874207, 2013). "We also assessed the tumor-suppressor activity of NTRK3 in xenografts in immunodeficient nu/nu nude mice." (PMID 23874207, 2013). "The dependence receptor aspect of the biological effects of NTRK3 suggests it has the potential to be either an oncogene or a tumor suppressor gene, depending on the presence of NT-3." (PMID 23874207, 2013). "Our findings demonstrate that NTRK3 may be a potential prognostic biomarker in BC, highlighting its importance in both tumor progression and patient survival." (PMID 40142285, 2025). "Furthermore, the association between high NTRK3 expression with low CD4+ T cell infiltration and poorer prognosis emphasizes the importance of the tumor-immune interaction in BC progression." (PMID 40142285, 2025). "Additionally, we examined the levels of NTRK2 and NTRK3 expression in patients diagnosed with BC who had tumours positive for HER2." (PMID 40061872, 2025). "Dendritic cells, CD4+ T cells, and CD8+ T cells play crucial roles in initiating and sustaining anti-tumor immunity, suggesting that NTRK3 may enhance immune surveillance and contribute to a more favorable immune landscape in BC." (PMID 40142285, 2025). "Additionally, functional studies using BC cell lines, including NTRK3 knockdown or overexpression experiments, will help elucidate its mechanistic role in tumor growth, immune evasion, and metastasis." (PMID 40142285, 2025). "TIMER data from TCGA showed NTRK3 expression level in specific tumor types." (PMID 40142285, 2025).
tumor (continued). "The positive correlation between NTRK3 expression and dendritic cells, CD4+ T cells, and CD8+ T cells indicates that NTRK3 may be involved in modulating immune responses in the tumor microenvironment." (PMID 40142285, 2025). "This discrepancy suggests that the role of NTRK3 in BC may be context-dependent, potentially varying based on tumor subtype, stage, or other molecular factors." (PMID 40142285, 2025). "CD4+ T cells are pivotal for orchestrating adaptive immunity, and their low infiltration in the context of high NTRK3 expression may suggest an immunosuppressive microenvironment that favors tumor progression." (PMID 40142285, 2025). "A previous study showed that NTRK3 may be a potential tumor suppressor gene in cancer via inactivated epigenetic and genetic mechanisms." (PMID 40142285, 2025). "Therefore, we studied a correlation between NTRK3 and tumor-infiltrating immune cells in various cancers, especially BC." (PMID 40142285, 2025). "Somatic intrachromosomal or interchromosomal rearrangements involving NTRK1, NTRK2, or NTRK3 may be found as oncogenic drivers in a wide range of tumor types." (PMID 39295960, 2024). "While DNA-based NGS alone may access for point mutations, fusions, and copy number changes, the sensitivity for NTRK3 is limited (76.9%) and is reliant on decent tumor purity." (PMID 38200576, 2024). "There were 20 (48.8%) NTRK1 and 21 (51.2%) NTRK3 fusions in 7 and 12 tumor types, respectively." (PMID 37567953, 2023). "This gene family encodes tropomyosin receptor kinases (TRKA, TRKB, and TRKC), and fused NTRK genes (NTRK1, NTRK2, NTRK3) translate a TRK fusion protein that activates tyrosine kinases and constitutively stimulates the growth of tumor cells." (PMID 37895255, 2023). "Even though they share a common ETV6::NTRK3 fusion, these high-grade adenocarcinomas might represent a neoplasm distinct from SC by morphology and immunoprofile." (PMID 37415052, 2023). "NTRK1 fusions were detected in three tumor samples, and two samples harbored NTRK3 fusions." (PMID 35681640, 2022). "In a clinical study of 25 patients who had various malignancies containing NTRK, ROS1, or ALK gene fuses and received an effective dose of entrectinib, an overall response rate of 79% with significant tumor regression in all NTRK-altered tumors (including ETv6: NTRK3 translocation) was observed." (PMID 35190738, 2022). "NTRK1 fusion was detected in three tumor samples, and two samples harbored NTRK3 fusions." (PMID 35681640, 2022). "For example, NTRK3 overexpression has been shown to induce apoptosis and tumor shrinkage in MB mouse models, and its inhibition in MBs-SHH may lead to tumor progression by increasing tumor cell survival." (PMID 35978432, 2022). "Furthermore, 23 newly NTRK1, NTRK2, and NTRK3 gene fusions were identified across different tumor types, including lung adenocarcinomas." (PMID 36289793, 2022). "Clinicopathologically, RET/PTC3 was associated with solid growth pattern and higher tumor aggressiveness, BRAFV600E and RET/PTC1 with classic papillary morphology and mild clinical phenotype, and ETV6ex4/NTRK3 with follicular-patterned PTC and reduced aggressiveness." (PMID 34282777, 2021). "On the other hand, one subject (#10) had a NTRK3 missense mutation in the primary tumor that was not seen in the metastatic lesion." (PMID 33716974, 2021). "Furthermore, NTRK1 fusion-positive carcinomas differed from carcinomas harboring the NTRK3 fusion gene by higher frequencies of tumor multifocality, distant metastases and carcinoma invasiveness." (PMID 33923728, 2021). "Clinicopathologically, RET/PTC3 was associated with solid growth pattern and higher tumor aggressiveness, BRAFV600E and RET/PTC1 with classic papillary morphology and mild clinical phenotype, and ETV6ex4/NTRK3 with follicular-patterned PTC and the reduced aggressiveness." (PMID 34282777, 2021).
tumor (continued). "Fusions of neurotrophic tropomyosin receptor kinase genes NTRK1, NTRK2 and NTRK3 with various partner genes occur in both common and rare tumours and are of paramount predictive value due to the availability of very effective pan-Trk inhibitors like Larotrectinib and Entrectinib." (PMID 34372873, 2021). "Therefore, in this report we examined the expression and function of miR-128-3p and NTRK3 in MM cells and found that miR-128-3p and NTRK3 proved to be tumor suppressor and oncogenes of MM cells, respectively." (PMID 33575204, 2020). "These disparate functions of NTRK3 might be due to differences in pathological changes within different tumor tissues." (PMID 33575204, 2020). "For example, tumor-agnostic biomarkers such as micro-satellite instability, oncogenes like NTRK1, NTRK2, and NTRK3, and the recently United States Food and Drug Administration (FDA)-approved tumor mutation burden, are used for tumor-agnostic patient stratification and therapeutic decisions." (PMID 33396205, 2020). "Finally, our results indicated that miR-128-3p can function as a tumor suppressor by inhibiting carcinogenesis of the oncogenic NTRK3." (PMID 33575204, 2020). "Through this screen, we found that neurotrophin tyrosine kinase receptor 3 (NTRK3) acts as either a tumor-suppressor gene or an oncogene in the development of various cancers and that its mutation status (mutant-type NTRK3, NTRK3-MT) can predict the prognosis of patients with LUAD treated with ICIs." (PMID 32903385, 2020). "In OSCC-GB also, NTRK3 is epigenetically dysregulated and appears to behave as a tumor suppressor." (PMID 33317464, 2020). "Further molecular analysis of the tumor tissue revealed an EML4:NTRK3 fusion." (PMID 33353026, 2020). "The downregulated profile of NTRK3 together with the functional in vitro test could possibly sustain a tumour-promoting role of this gene." (PMID 30857282, 2019). "Further research for a specific NTRK3 tyrosine kinase inhibitor could lead to the discovery of a new targeted treatment of this tumor." (PMID 30852371, 2019). "NTRK3 is a conditional tumor suppressor epigenetically or genetically downregulated in CRC." (PMID 31812953, 2019). "Thus, the discovery of mutant, as well as methylated, NTRK3 in CRC suggested the possibility of NTRK3 being a CRC tumor suppressor gene." (PMID 23874207, 2013). "Taken together, these results provide support for a tumor suppressor role for NTRK3 in CRC." (PMID 23874207, 2013). "Induced NTRK3 expression in the absence of its ligand, NT-3, causes apoptosis and suppresses in vitro anchorage-independent colony formation and in vivo tumor growth." (PMID 23874207, 2013). "Additionally, lncRNA LINC00978 could contribute to tumor development by regulating the microRNA-497/NTRK3 axis in GC." (PMID 35794986, 2022). "Having established that miR-128-3p and NTRK3 functioned as a tumor suppressor and an oncogene, respectively, and that NTRK3 was a target of miR-128-3p, the next issue to address was whether miR-128-3p exerted a tumor inhibitor effect by hindering carcinogenesis of the oncogenic NTRK3." (PMID 33575204, 2020). "With regards to the possibility that NTRK3 could act as a tumor suppressor gene in the colon rather than as an oncogene, somatic inactivating mutations of NTRK3 have been identified in CRC, as well as in other cancers including breast, lung, and pancreatic." (PMID 23874207, 2013). "This discovery led us to assess whether NTRK3 could be a tumor suppressor gene in the colon." (PMID 23874207, 2013). "Fluorescence in situ hybridisation (FISH) was positive in 17 of 17 tested tumours (14 ETV6‐NTRK3 dual‐fusion; 3 NTRK3 break‐apart)." (PMID 41195654, 2025). "We detected kinase fusion in 2 cases (3.2%) of the tumours: RET fusion in 1 case, and NTRK3 fusion in another case." (PMID 40144205, 2025). "Gene fusions primarily comprising RET, NTRK1 or NTRK3 and more rarely ALK or MET genes are among the most commonly described as tumor drivers in pediatric PTC." (PMID 40338900, 2025).
tumor (continued). "In another study, DOG1 expression was noted along the luminal surface of tumor cells in one-third of salivary SCs with atypical FISH signal patterns using break-apart and ETV6::NTRK3 fusion probes." (PMID 39101978, 2024). "The proteins PLK1, SPIB, and CD24 show darker staining in tumor tissues, while NTRK3 and EDA2R exhibit lighter staining in tumor tissues." (PMID 39596658, 2024). "This study showed that, across all tumor types, most NTRK fusion genes involved NTRK1 (49.5%) or NTRK3 (44.2%)." (PMID 38925616, 2024). "In this regard, it would be interesting to evaluate a combined therapy with dasatinib and recently identified DSRCT therapeutic targets NTRK3 or SIK1, which target the bulk tumor cells." (PMID 38177125, 2024). "In clinical tumor tissues, protein expression of SPIB, PLK1, and CD24 was up-regulated, while protein expression of NTRK3 and EDA2R was down-regulated." (PMID 39596658, 2024). "From our tumor bank, we were able to obtain 39 samples with NTRK1 or NTRK3 fusions in which the presence of alteration was confirmed by variant-specific PCR or NGS." (PMID 37762506, 2023). "The TRK family includes TRKA, TRKB, and TRKC proteins, encoded by the neurotrophic receptor tyrosine kinase 1 (NTRK1), NTRK2, and NTRK3 genes, respectively, and these NTRK gene fusions are oncogenic drivers of various adult and pediatric tumor types." (PMID 36770611, 2023). "Using FISH, three tumors met the criteria of ≥ 10% tumor cells with break apart signals, including the ETV6::NTRK3 fusion." (PMID 37067589, 2023). "While the analysis of ALK, ROS1, and RET rearrangements is generally limited to several tumor types, NTRK1, NTRK2, and NTRK3 are currently positioned as “agnostic” targets, calling, in theory, for systematic testing of the wide spectrum of tumors." (PMID 37762506, 2023). "Collectively, the anti-tumor immunity in NTRK1/2/3 MT NSCLC was enhanced in some aspect compared with their WT counterparts, especially in patients with NTRK3 MT." (PMID 38031067, 2023). "All NTRK-rearranged neoplasms are characterized by immunohistochemical positivity for CD34 and S100 and, molecularly, by fusions of NTRK1, NTRK2, and NTRK3 genes with variable partners; alternative RAF1 and BRAF fusions have also been described." (PMID 37876963, 2023). "The model showed that patients with lower tumor stage, higher RAC1 methylation levels, WT NTRK3, higher Tr cell infiltration in the TME, and RASA1 CNV survived better than other patients with opposite status." (PMID 35936718, 2022). "Among the genes upregulated in the atypical tumor compared to the nevus were: SOX10, the receptor tyrosine kinases ROS1 and NTRK3, PLA2G2A, and HOXA11, while DUSP2, PDGFD, and ELN were downregulated." (PMID 35052351, 2021). "TrkC/NTRK3 is a member of the NTRK neurotrophin tyrosine kinase receptor family and functions as a tumor suppressor." (PMID 32083000, 2020). "In patient 9, SMO, NTRK3, IDH2, IGF1R, and CDK12 were also amplified in tumour #1 in addition to ERBB2 amplification." (PMID 31929516, 2020). "Previous studies have indicated that NTRK3 affects multiple signaling pathways, including the MAPK and PI3K pathways, which further promote cell differentiation and affect tumor progression." (PMID 32903385, 2020). "Meanwhile, the immunohistochemistry results found that tumor formed by LINC00052-deplted cells showed increased expression of proliferation marker Ki-67 and decreased expression of NTRK3." (PMID 27351280, 2016). "Alterations in the expression of NTRK3 and its fusion proteins may profoundly impact processes like epithelial–mesenchymal transition (EMT), tumour growth rate, and tumourigenesis." (PMID 40061872, 2025). "We did not identify any patients with an ELM4::NTRK3 gene fusion tumor as previously found by others." (PMID 38967220, 2024). "NTRK3 has been described in important cancer related pathways that promote both survival and cell proliferation and so its role as an oncogene and tumour suppressor is not unexpected." (PMID 38475971, 2024).
tumor (continued). "A false‐negative IHC result was observed in particular for cases carrying NTRK3 rearrangements, regardless of the tumor type." (PMID 37143440, 2023). "Among the other two tumors with strong Pan-TRK expression, the NTRK1, NTRK2 or NTRK3 rearrangement was negative in one tumor (case #4), and no rearrangement was evaluated because of the poor DNA quality in the other sample (case #5)." (PMID 36612101, 2022). "In addition, the results of bioinformatics analysis showed that the top markedly enriched pathway for these HERV-K (HML-2) gag loci was the activation of the NTRK3 signal, and the NTRK fusion gene was one of the tumor-driving genes." (PMID 35359739, 2022). "TRK staining in ≥1% of tumor cells is considered NTRK fusion-positive to increase sensitivity, as NTRK3 fusion-positive tumors may show focal or weak expression." (PMID 34531526, 2022). "Tumor samples from 31 patients were tested for NTRK1, NTRK2, and NTRK3 fusion by FISH analysis." (PMID 35681640, 2022). "Abnormal activation of NTRK3 and its fusion proteins may regulate the epithelial-mesenchymal transition (EMT) process, tumor growth rate and tumorigenicity by activating several signaling pathways." (PMID 33894748, 2021). "Unusual activation of NTRK3 and its fusion proteins may balance the epithelial–mesenchymal transition (EMT), oncogenicity, and tumor growth rate via triggering various signalling pathways." (PMID 35141152, 2021). "This means that NTRK3 inhibited HCC cells invasion and migration, and it might work as a tumor suppressor in HCC." (PMID 27351280, 2016). "Although somatic mutations of NTRK3 that are predicted to inactivate function have been observed in CRC, NTRK3's role as a tumor suppressor gene in CRC has not been clearly demonstrated to date." (PMID 23874207, 2013). "We have provided evidence that NTRK3 can trigger apoptosis and inhibit tumor growth in the absence of its ligand NT-3 and that these effects are reversed by the addition of NT-3." (PMID 23874207, 2013). "Furthermore, the only tumor with a non-altered expression pattern carried a translocation in the NTRK3 gene; alterations in this kinase are not always accompanied by changes in the 5′/3′-end transcript ratio." (PMID 37686416, 2023). "Furthermore, SLITRK3 amplification recurring in LUSC at a frequency of 30% with the mechanistic role we have uncovered can explain why a previous tumor immunostaining study reported NTRK3 protein is absent in LUAD samples but detected in approximately 30% of LUSC samples." (PMID 35006496, 2021). "Polyploidy was detected in most tumor cells using the NTRK1 break-apart probe in case #6, but no rearrangement of NTRK1, NTRK2, or NTRK3 was detected using the three break-apart probes." (PMID 36612101, 2022). "Another tumor (case #7) with weak-moderate expression of Pan-TRK was negative for NTRK1, NTRK2 and NTRK3 rearrangements." (PMID 36612101, 2022). "In summary, we report 2 cases of a high-grade tumor diagnosed as non-ITAC of the sinonasal region, characterized by overt hypercellularity, largely solid growth pattern with comedo-like necrosis, immunohistochemical positivity for p40/p63, S100, SOX10, and GATA3, with a recurrent ETV6::NTRK3 fusion." (PMID 37415052, 2023). "Moreover, this tumor was negative for NTRK2 and NTRK3 rearrangements." (PMID 36612101, 2022). "Using patient demographics, tumor characteristics, and CGP, we show that GIST lacking alterations in canonical genes occur in younger patients, frequently metastasize to lymph nodes, and most contain deleterious genomic alterations, including gene fusions involving FGFR1 and NTRK3." (PMID 27974047, 2016).